IL2 (interleukin 2)
Diseases named in the same sentence as IL2 in open-access papers (continued):
Sharing a sentence is not in itself a finding about the gene and the disease.
tumor (continued). "When a single dose of replicon was administered 7 days post tumor inoculation, the Ab1c1 mutant IL-2-expressing replicon significantly slowed tumor progression compared to either the ABC IL-2 replicon, the ABC replicon without IL-2, or the vehicle control." (PMID 31061426, 2019). "Strikingly, when mice were treated with IL-2-neutralizing mAb prior to both i.n. administration with L. casei BL23 and s.c. challenge with TC-1 cells, L. casei BL23 failed to protect against TC-1 tumor onset." (PMID 30687269, 2018). "The absence of a potent direct anti-tumor activity of IL-12/15/18 pre-activated NK cells in these mouse studies might be due to the lack of host CD4 T cells and insufficient IL-2 that may be instrumental in maintaining durable anti-tumor responses." (PMID 30546366, 2018). "However, various randomized trials of adjuvant therapy involving tumor cells plus BCG, tumor cell vaccination, IFN-α, high-dose IL-2, or a combination of cytokines have not demonstrated survival benefit when compared with observation." (PMID 28061473, 2017). "Naturally occurring tumour‐specific HLA‐II‐restricted CD4+ T cells and those engineered to express HLA‐I‐restricted tumour TCRs have been reported to exhibit a mainly Th1 phenotype, where cells typically produce IFN‐γ, TNF‐α and IL‐2 but not IL‐4, IL‐5 or IL‐10." (PMID 27324616, 2017). "It is upregulated by IL-2, and mediates non-MHC-restricted tumor cell lysis." (PMID 27861156, 2016). "Earlier observations have determined that IL-2-dependent activities of CD8+ T cells are not directly affected by hAAT; we therefore suggest that hAAT-induced changes in the intra-tumor inflammatory gene profile are primarily mediated by innate leukocytes, such as macrophages." (PMID 28003813, 2016). "Compared with controls, tumor cell vaccines co-expression anti-PD-1 mAbs and GM-CSF not only release the inhibition state of PD-1+ TIL in tumor microenvironment and promote the proliferation but also facilitate IFN-γ, TNF-α and IL-2 secretion of TIL (data not shown)." (PMID 29263903, 2016). "Taken together, these data suggest that both PD-1 expressing T cells and Treg cells within the tumor may have a suppressive effect on T cells secreting IFN-γ, IL-2, or TNF-α, but not Th17 cells." (PMID 27014625, 2016). "At the same time, however, the level of putative non-DC target (tumor) cells, identified as CD11c- cells presenting the OVA-derived peptide SIINFEKL in context of MHC class I, was significantly lower in IFN-α2 and IL-2-injected tumors compared to non-injected controls on day 14 post-transfer." (PMID 26107883, 2015). "Similarly, tumor and anti-CD16mAb mediated split anergized NK cells lose CD16 receptors and addition of IL-2 does not fully reverse down-modulation of CD16 receptor (data not shown)." (PMID 26247631, 2015). "Tumor resistance to NK cell-mediated killing induced by IL-2 + anti-CD16mAb + sAJ2-treated NK cells is induced by combination of IFN-γ and TNF-α since antibodies to both, and not each cytokine alone, were able to restore tumor sensitivity to NK cells." (PMID 26697005, 2015). "Interestingly, the levels of tumor-infiltrating pentamer-positive CD8+ T-cells were lower in IFN-γ–treated mice compared to PBS-injected controls on day 4 post-transfer and in IL-2-injected mice compared to non-injected controls on day 14 post-transfer." (PMID 26107883, 2015). "In addition, the number of tumor-infiltrating natural killer (NK) cells was increased in IFN-α2 and IL-2 treated mice compared to non-injected and PBS controls." (PMID 26107883, 2015). "C4-27z CAR T cells produced significant amounts of IFN-γ and IL-2 after coculture with all αFRpos cancer cell lines, but not when cultured with αFRneg cells, indicating that C4 CAR T cells functionally recognize αFRpos tumor cells." (PMID 26101914, 2015).
tumor (continued). "We consistently observed that splenocytes expanded in IL-2 or IL-21 alone did not expand well, were not effective at curing B16 metastases compared to controls, and did not produce IFN-γ when exposed to B16 tumor cells to a significantly different level compared to controls." (PMID 25903148, 2015). "With IL-2 and resveratrol co-treatment, the expression levels of FoxO1 were not different from the resveratrol treatment alone, which suggest that IL-2 does not directly affect the expression of FoxO1 in B16F10 tumor cells." (PMID 22532866, 2012). "Interestingly, immunostaining revealed IL-2 protein expression in the background cells of lymphoma tumors, but not in the ALCL tumor cells themselves." (PMID 23675235, 2011). "NK cells are large granular lymphocytes that express neither α/β or γ/δ TCR nor CD3 on their surface, can lyse a number of different tumour cells and may be stimulated by IFN-γ, IL2, IL12 and IL18." (PMID 20500874, 2010). "Although intralesional IL-2 levels were not measured in the present study, the increased expression of CD25 on epithelial cells suggests that IL-2 may control tumour progression." (PMID 19689792, 2009). "IL-2 and IL-13 were not correlated with PR status, whereas IL-1β, IL-6, IL-8, IL-10, IFN-γ, MCP-1, MIP-1β, TNF-α and, to a lesser extent, IL-4, IL-12 and G-CSF were more abundant in PR-negative tumours than in PR-positive ones." (PMID 17261184, 2007). "It is possible that the limited IL-2 production by intratumoral CD4+ T cells could be in part due to GSDMD inactivation, since a portion of CD4+ T cells did not display GSDMD activation in tumor sections." (PMID 40759573, 2025). "Co-culture with B16 ffLuc GFP EGFR cells for 24 h induced the secretion of approximately 4 pg/mL of IL-2 and 3.5 × 103 pg/mL of interferon-gamma (IFN-γ) by EGFR mCAR T cells, while no significant cytokine release was detected in cultures without antigen-positive tumor cells." (PMID 41516067, 2025). "Evaluating the phenotypic composition of the CD8+ T cells infiltrating tumor, we observed that at 48-hours after ALT administration, the endogenous CD8+ T cell phenotypes in tumors were similar, regardless of whether ALT was expanded with IL-2 or IL-7." (PMID 40244705, 2025). "However, it is also notable that a series of genes that are expressed in activated CD8+ T cells (Gzmb, Prf1, Il2, Ifng, Tnf, Fasl) or in activated CD4+ T cells (Tgfb1, Cd40lg, Il2, Ifng, Tnf, Fasl) were not upregulated in the relevant CD8+ and CD4+ clusters in tumours versus normal." (PMID 40473819, 2025). "Other enriched gene sets included TNFA signaling, IL-2 STAT5 signaling, hypoxia, angiogenesis and negative regulation of apoptotic signaling, which may play important roles for TAC-T cells in lysing tumor cells and surviving in the immunosuppressive microenvironment." (PMID 39735536, 2024). "Interestingly, in WT mice receiving EMT6 and Fab anti-CD200R, no tumor cells were detectable after immunotherapy (tumor cell vaccination), and the CD4+ cells produced increased TNFα/IL-2/IFNγ on stimulation with EMT6 in vitro, as had been seen already in CD200RKO mice." (PMID 38540350, 2024). "Importantly, combination of imiquimod and IL-2 without peptide and CD3 bsAb did not result in better survival outcomes compared to CD3xTRP1 alone, indicating that addition of the vaccine peptide is required for the anti-tumor activity." (PMID 38167722, 2024). "However, it is important to emphasize that T cell depletion mediated by IL-2 does not contradict its role in antitumor activity, since this cytokine is essential to promote CTL activity and proliferation during the initial stages of tumor development." (PMID 36674504, 2023). "In contrast, a clear reduction in tumor cells was observed after 4 to 12 hours when they were co-incubated with TKD/IL-2 activated NK cells, after 24 hours when they were co-incubated with anti-Hsp70 CAR T cells, and after 36 hours nearly no viable tumor cell was visible." (PMID 35720311, 2022).
tumor (continued). "Combinatorial administration of anti-CTLA-4 with IL-2Cx, a complex of IL-2/anti-IL-2 which directs IL-2 to NK and CD8+ T cells but not Tregs, or IL-15/IL-15Ralpha complexes further tips the tumoral effector/regulatory cell ratio in favor of activated NK cells and enhances tumor control." (PMID 33995422, 2021). "Adding the induced Treg by tumor explants with or without anti-PD-1 or/and anti-IL-21 treatment strongly inhibited the proliferation of responder T cells (both CD4 and CD8), reduced the IFN-γ, IL-2 levels of CD4+ T cells, and cytotoxicity, GranzymeB, Perforin levels of CD8+ T cells." (PMID 34026621, 2021). "CD38 CAR-T cells secreted large amounts of TNF-α, IFN-γ, IL-2 and granzyme when incubated with CD38-positive tumor cells compared with pan-T cells, and there was no significant change in the killing effect of CD38 CAR-T cells on tumor cells that did not express CD38." (PMID 34513682, 2021). "had previously shown that tumor-specific tolerant T cells, which failed to proliferate in vitro, could be rescued by incubation in medium containing high-dose IL15 (or, less efficiently, IL2)." (PMID 33796916, 2021). "Similarly, in in vivo experiment on Balb/c mice injected with EMT6/P cells, the combination MET+CUR decreased tumor size but only trends for increase of IFN-γ and for significant decrease of IL-4 were detected, while IL-2 and IL-10 level did not change significantly." (PMID 30959898, 2019). "It is, however, possible that qualitative differences in immune responses between different cytokines masked the cytokine-specific role of MHC-I expression in anti-tumor efficacy, i.e. whereas therapeutic efficacy with IFN-γ may depend on MHC-I, efficacy with IFN-α2 and IL-2 might not." (PMID 26107883, 2015). "Indeed, even if some tumor antigen specific CD4 Treg clones were also found to secrete a diverse panel of cytokines such as IFN-γ, GM-CSF, TNF and IL5 or IL4 and IL10, in vitro, none of them was able to secrete IL2." (PMID 23284752, 2012). "However, whether IL-2 signaling has functional consequences in ALCL cells has not yet been explored, despite the high-level expression of surface CD25 in tumor cells." (PMID 23675235, 2011). "In order to investigate whether T cells capable of recognizing the malignant cells are present in the tumor, TILs were isolated from 25 NPC biopsies and then expand in medium containing low doses of IL-2 without additional stimulation until the cell number was sufficient for analysis." (PMID 17987110, 2007). "However, IL-2 is not well tolerated systemically, resulting in the creation of Darleukin (L19IL2), a fusion protein of IL-2 to L19, a monoclonal antibody that targets an angiogenesis marker, allowing for preferential delivery of the IL-2 cytokine to tumor cells." (PMID 38893078, 2024). "Indeed, it is rare to see tumour rejection or cure in NSG mice in CAR-T cell studies against solid tumours where mice only receive CAR-T cells with no additional treatment (e.g. checkpoint inhibitors, radiation, IL-2 administration) or where there is no modification of tumour cells." (PMID 37684239, 2023). "However, magnitude of the response expressed as populations of IFN-γ/IL-2/TNF-γ producing TERT6- and TERT8-specific CD4+ and CD8+ T cells showed no inverse correlation to the size of the rtTERT-expressing tumors (i.e., it was not a decisive factor in tumor rejection)." (PMID 32570805, 2020). "However, IL-2 can also lead to activation-induced cell death (AICD), progressive differentiation (i.e. less “young” TIL) and to the induction of suppressive regulatory T cells (Tregs), indicating that IL-2 may also have a negative impact on the induction of an effective anti-tumor response." (PMID 23402380, 2013).
cancer (1,554 papers, 1987 to 2026). A tumor composed of atypical neoplastic, often pleomorphic cells that invade other tissues. "The combination of RT and modified IL-2 variants has achieved potent anti-cancer responses in both preclinical models as well as in clinical trials and is proving to be an efficacious therapeutic combination." (PMID 40502703, 2025). "For example, mRNA encoding IL2RG, the gamma subunit common to the IL-2, IL-4, IL-7 and IL-21 receptors, is overexpressed by 155% in platelet-educated cancer cells." (PMID 40096084, 2025). "Herein, we focus on discussing the impact and relevance of anti-cancer immune effectors induced by IL-2 immunotoxins (IT), IL-2 immunocytokines, and IL-2 derivatives or variants in different combined therapies." (PMID 39852848, 2025). "Th1 cells release IL-2, which plays an essential and recursive role in causing the production of other cytokines that are essential to fight cancer." (PMID 40806447, 2025). "Clinical trials of receptor‐biased interleukin‐2 (IL‐2) variants in cancer therapy show limited efficacy." (PMID 40108893, 2025). "The therapeutic benefits of IL2 regarding cancer are often associated with severe toxicities, supporting Tregs were reported to play critical roles in suppressing the immune response." (PMID 41050655, 2025). "As a result, there is an overall enhancement of the immune response, further supporting the combination of IL‐2 variants for optimizing immune activation in cancer therapy." (PMID 40108893, 2025). "Firstly, most studies using IL-2 and/or GM-CSF as adjuvants have been associated with cancer vaccines and influences on the outcomes in various cancer models (human or animal)." (PMID 38605961, 2024). "Gene set enrichment analysis of TempO‐Seq data showed higher expression of genes associated with hallmarks of cancer pathways including epithelial to mesenchymal transition (p < 0.001), IL2 STAT5 signalling (p = 0.007), and angiogenesis (p = 0.017) in TMS3." (PMID 38650367, 2024). "In a recent meta-analysis of 24 studies with 6,936 ICI-treated cancer patients, IL-2 levels were significantly associated with longer OS, and inversely, IL-6 and IL-8 levels were with shorter OS." (PMID 38799450, 2024). "A notable association was observed between IL-2 levels and the prognosis of patients diagnosed with pan-cancer." (PMID 38720108, 2024). "While IL‐2 is currently used in the clinic to treat certain types of cancer, the high toxicity associated with its use has prevented its wider application." (PMID 35246947, 2023). "As we continue to investigate the role of IL-2 and IL-2R in tumorigenesis, there is also growing interest in their potential as diagnostic, prognostic, and monitoring biomarkers in cancer." (PMID 37516849, 2023). "The administration of LAKs and large doses of IL-2 in patients with various types of cancer have been reported to cause cancer regressions and significantly enhance antitumor response in preclinical studies and clinical trials." (PMID 37345057, 2023). "The increase of Tregs after immunization with peptide vaccines together with cytokines (GM-CSF or IL-2), was also described in patients with different types of cancer carrying a mutated Ras." (PMID 37122717, 2023). "In NSCLC and other cancers, increases in TNFɑ alone and TNFɑ, IFNγ, and IL2 together are associated with increased Th1 polarization post DC vaccination." (PMID 37830618, 2023). "LCP2 is involved in T cell activation and can increase the IL-2 gene promoter activity following transient overexpression, which is associated with better prognosis of cancer patients." (PMID 37500893, 2023). "ALT-803, another engineered IL-2 variant, is under clinical trial for treating various cancers, showing promise in preclinical models of multiple myeloma [ClinicalTrials.gov Identifier: NCT02099539]." (PMID 37516849, 2023).
cancer (continued). "This review discusses the pivotal roles of IL-2 and IL-2R in tumorigenesis, shedding light on their potential as diagnostic and prognostic markers and their therapeutic manipulation in cancer." (PMID 37516849, 2023). "CUE Biopharma developed Immuno-Selective Targeting and Alteration of T cells (Immuno-STATs), which were originally designed to prime and expand naïve and pre-existing anti-cancer T cell repertoires by co-delivering an engineered IL-2 variant (IL-2v)." (PMID 37568582, 2023). "Although the systematic distribution of high doses of IL-2 has been used in cancer treatment since 1998, this therapy is associated with high toxicity and moderate antitumor activity." (PMID 37046608, 2023). "IFN‐γ and IL‐2 are key effector molecules linked to type‐1 pro‐inflammatory immune responses mediated by the CD8+ T cells directed towards cancer cells." (PMID 37249301, 2023). "In 1992, a laboratory-made form of IL-2 was the first immunotherapy approved to treat cancer, but its intravenous administration causes severe side effects, limiting its use." (PMID 38011277, 2023). "IL-2 administration in humans can cause severe toxicity and can lead to regulatory T-cell activation, which is an undesired effect in the context of cancer immunotherapy due to their counterproductive inhibitory effect on cytotoxic lymphocytes." (PMID 35287669, 2022). "It has been widely demonstrated that the overexpression of CTLA-4 is associated with reduced interleukin-2 (IL-2) expression and T-cell cycle arrest, resulting in the reduction of T-cell function and immune evasion of cancer cells." (PMID 36698392, 2022). "A major drawback of IL-2 for cancer immunotherapy includes its high toxicity, which often causes life-threatening conditions in patients." (PMID 35651800, 2022). "C-Myc has been shown to act as a transcription factor that induces the transcription of genes encoding cytokines, including IL-2, IL-13 and IL-17C, in cancer cells." (PMID 35954273, 2022). "Elastin treatment of GPX4-knockout cancer cells is strongly associated with immune pathways such as the IL-1 and IL-2 pathways." (PMID 34975326, 2022). "Alternatively, low doses of IL-2 preferentially target IL-2Rα on Treg cells, restricting the immune response, and are associated with poor prognosis in patients with cancer." (PMID 35104808, 2022). "Before evaluating WNK3 and SIK3, we first confirmed that H460 and H2009 cells stably expressing shPD-L1 exhibited increased susceptibility (decreased cancer cell viability) to IL-2 and anti-CD3-activated peripheral blood mononuclear cells (PBMCs)." (PMID 36357569, 2022). "The IL2-Smurf2 chimeric protein effectively and specifically caused death by targeting cancer cells, thus opening new approaches in the fight against cancer." (PMID 36612252, 2022). "IL2-Smurf2 has the ability to enter target cancer cells, cause mass protein degradation and thereby lead to apoptotic cell death, while not harming non-target cells." (PMID 36612252, 2022). "The developed mutant IL-2 can be an alternative tool in IL-2 associated immunotherapy of various cancers." (PMID 35354847, 2022). "Of note, IL-2 has been investigated as a viable therapeutic modality to treat underlying autoimmune pathologies, cancer, hypersensitivity responses, and allograft rejection." (PMID 35954285, 2022). "Interleukin-2 (IL-2)-based immunotherapy is an efficient therapy that promotes immune system activity against cancers but is associated with toxicity." (PMID 35874707, 2022). "IL-2 associated with T cell proliferation can be activated by IL-2Rα signaling in vivo and can contribute to cancer immunotherapy." (PMID 34959271, 2021). "All the selected miRNAs showed overlap in regulation in pathways associated with cancer, IL-2 signaling, TGF-β signaling as well as BDNF signaling pathway." (PMID 35145424, 2021). "All selected miRNAs showed overlap in regulation in pathways associated with cancer, IL-2 signaling, TGF-β signaling as well as BDNF signaling pathway." (PMID 35145424, 2021).